CD163 (CD163 molecule)
Diseases named in the same sentence as CD163 in open-access papers (continued):
Sharing a sentence is not in itself a finding about the gene and the disease.
tumor (continued). "Previous studies have shown that the abnormal expression of CD163 affects tumor development in cancers." (PMID 36551651, 2022). "More interestingly, immunofluorescence double staining was conducted, and the tumor tissue-accumulated macrophages were CD68+CD163+ macrophages (M2-polarized macrophages), indicating a greater importance of the M2 subtype in OSCC progression." (PMID 35090495, 2022). "The IHC analysis indicated that higher in tumor tissues expressed higher CD163+TREM2+ compared with para-tumor did." (PMID 35017463, 2022). "In malignant ascites, TAMs float separately or are located in the center of spheroids surrounded by tumor cells; they possess M2 polarization by the abundant expression of CD163 and CD206." (PMID 35682890, 2022). "IHC staining showed infiltration of CD163+ cells was higher in RCC and infiltration of CD163+ cells was higher in tumor, paratumor and normal tissues of RCC." (PMID 35936748, 2022). "Nevertheless, IHC was performed in consecutive sections, and visual analysis suggested similar CD68 and CD163 expression profiles in the same tumor sample, although CD68 seemed to be expressed in a larger proportion of macrophages." (PMID 36230752, 2022). "Gene expression of TYMP and CD163 was analyzed in snap-frozen tumor tissues and in microdissected formalin-fixed tumor tissues separated into tumor epithelium and stroma." (PMID 35567733, 2022). "TREM2 binding to its ligand promotes high expression of CD163 in tumor-associated macrophages, amplifying the inflammatory response in the local TME and promoting tumorigenesis and tumor progression." (PMID 36438899, 2022). "CD163+M2 macrophages and Foxp3+Tregs were mainly distributed in the interstitium of tumor tissues and lymphocyte aggregates in PTC and mainly scattered around cancer cells in ATC." (PMID 35222534, 2022). "Amount of CD163+ TAMs negatively correlated with Tap73 expression and positively correlated with tumor grade." (PMID 36686729, 2022). "Elevated levels of CD163+ TAMs in tumor stroma and tumor nest correlated with poor prognosis in 107 patients with triple negative breast cancer operated on at Dokkyo Medical University Hospital." (PMID 36686729, 2022). "As expected, the traditional count of CD163+ TAMs in the tumor core and the proportion of CD163+ TAMs among stromal cells were highly correlated (coefficient = 0.74; 95% CI: 0.69; 0.78)." (PMID 35053472, 2022). "It was observed that CD163 positive cells were obviously more in tumor tissues than in adjacent tissues." (PMID 35897096, 2022). "An objective and automated algorithm was developed to phenotype CD163+ TAMs and calculate their density within the tumor stroma and derive several spatial metrics of interaction with cancer cells." (PMID 35053472, 2022). "Tumor-associated macrophages (TAM) are frequently polarized toward a M2 phenotype, which express CD68 and CD163." (PMID 35248056, 2022). "In this study, we analyzed TYMP and CD163 expression in micro- and macrodissected tumor tissue from 312 patients with stage II CRC." (PMID 35567733, 2022). "CD163+cells were frequently scattered as single elements throughout the tumor; aggregates were instead more frequently observed near areas of necrosis." (PMID 35937296, 2022). "This is all in line with previous studies in which the density of M2 TAMs, usually CD163+ cells, seems to be correlated to the tumor proliferation, metastatic process and poor outcome." (PMID 35326631, 2022). "Specially, we stained CD68 with green fluorescence and stained CD86 or CD163 with red fluorescence in the tumour tissues by IF co‐localization assay." (PMID 34964155, 2022). "Comparing immune cell infiltration in the peritumoral area and tumor core of glioblastomas showed that CD163+ cells were more abundant in the tumor core." (PMID 35464481, 2022).
tumor (continued). "Subsequently, IHC results of the tumor tissues showed that compared with the mTHP-1 + N group, the CD163 positive cells in the tumor tissues of the mTHP-1 + H group were prominently more." (PMID 35897096, 2022). "Pearson correlation analysis further showed that OPN was positively associated with M2 macrophage markers (CD163, VSIG4, MS4A4A, CX3CR1, and MRC1) and tumor-associated macrophage (TAM) markers (CCL2, CD68, and IL10)." (PMID 35669197, 2022). "These evidences manifested that CD68+CD163+M2-like macrophages in peripheral blood were different from the alternatively activated M2 macrophages in issue or tumor microenvironment." (PMID 35928634, 2022). "First, IHC for Iba1 and CD163 was performed in all cases (n = 56), and the cell densities in the tumor area were evaluated." (PMID 35132816, 2022). "In the current study, we observed a correlation between EMR1-TC and CD68+/CD163+ TAMs; EMR1-TC was a high-risk factor for tumor recurrence, especially in patients with macrophage-rich CRC." (PMID 36551877, 2022). "In our clinical study enrolling 60 HNSCC patients, we showed a high infiltration of CD68+ cells mainly composed of CD163+ M2 macrophages (more than 60%) in tumor patients." (PMID 35742830, 2022). "A high TAM density is associated with a poor prognosis in BC and surface expression of CD163 correlates with tumor progression and worsened prognosis." (PMID 35053451, 2022). "Deletion of ADAM17 gene inhibited tumor growth, increased the survival in tumor-bearing mouse models, and resulted in a significant decrease in CD163+ cell population." (PMID 36466812, 2022). "To detect the effect of CXCL1 on the tumor microenvironment, we examined CD4, CD8, and CD163 expression in tumor tissues of each group of mice." (PMID 36434686, 2022). "In conclusion, our findings revealed that CD163-expressing macrophages near tumor epithelial cells had high expression in poorly differentiated and T4 tumors." (PMID 35567733, 2022). "We previously reported that a peculiar population of tumor-infiltrating macrophages, characterized by the co-expression of CD163, CD33 and PD-L1, was present in the tumor microenvironment of HPD patients." (PMID 36555441, 2022). "A higher density of CD163+ TAMs was found in tumor tissues with stronger EZH2 staining, showing a significant positive correlation." (PMID 36038549, 2022). "Tumor stroma rich in ERα36high CAFs was correlated with high Ki67 expression (p = 0.041) and tumor-associated macrophages markers (CD68 and CD163, p = 0.041 for both)." (PMID 35454913, 2022). "An additional type of cluster interaction that was significantly higher within the tumor area of brain metastases involves CD3+p-STAT3– T cells with both CD163+p-STAT3– macrophages and CD11c+CD163+p-STAT3– cells (P = 0.018)." (PMID 35316217, 2022). "Several studies confirmed that tumor-supporting effect of CD163+ TAMs is mediated by the activation of STAT3 signaling pathway." (PMID 36686729, 2022). "They found that these agents drove the tumor microenvironment toward the pro-M2 microenvironment via an increase in Arg and CD163." (PMID 36230500, 2022). "In clinical trials, low-dose metformin recruits a greater number of CD8+ cytotoxic T lymphocyte and CD20+ B lymphocyte while enhancing tumor-suppressive (CD11c+) and reducing tumor-promoting (CD163+) macrophages in TME." (PMID 36679904, 2022). "In particular, an increased density of total CD8+ T lymphocytes, CD68+ macrophages and CD163+ TAMs was observed in the peri-tumoral stroma and within the tumor nests." (PMID 36123711, 2022). "In the majority of the cases analyzed, we found that cells with suppressor phenotypes (i.e., CD163+ and FoxP3+ cells) are abundant in the tumor, only in the presence of high frequencies of cells with cytotoxic effector phenotypes (i.e., CD8+ cells)." (PMID 36551693, 2022).
tumor (continued). "GBM tissue samples were subjected to immunohistochemistry for CD68 and CD163 in order to evaluate total and M2 macrophages, respectively, in both the center side of the tumor and in the healthy surrounding areas." (PMID 36611806, 2022). "Patients with high CD163 expression were remarkably correlated with clinicopathological characteristics including tumour size or tumour differentiation and high CD163 expression was an adverse predictor for RFS and OS." (PMID 34964155, 2022). "Previous studies have performed their analyses on CD163 related to the number, distribution, and phenotype comparing tumor and normal tissue/patients." (PMID 36551651, 2022). "Tregs are recruited through the binding of CCR4 on Tregs surface and CCL22 released by GBM tumor cells and CD163+ TAMs, induced by tumor-derived CCL20 and osteoprotegerin." (PMID 35269652, 2022). "Several approaches targeting CD163+ pro-tumor macrophages and/or immune suppressive FoxP3+ have been associated with an improved response to immunotherapy and/or chemotherapy and are in pre-clinical or clinical development." (PMID 36551693, 2022). "The finding that CD163+ cells in tumor adjacent normal epithelia was more prognostic than CD163+ cells within the tumor core was unexpected and striking in magnitude." (PMID 35075795, 2022). "The mean CD163 gene expression in macrodissected tumor tissues (macCD163), microdissected tumor epithelial cells (tecCD163), and microdissected tumor stroma (stromaCD163) was 0.13 ± 0.25, 0.06 ± 0.09, and 0.11 ± 0.22, respectively." (PMID 35567733, 2022). "Favorable features for the HER2+ cohort were determined by the ML model as the independent ratios of CD8, CD163, and PD-L1 in the lymphocytic region, CD163 ration in the tumor area, and the HER2/CEP17 ratio." (PMID 35892487, 2022). "Based on these findings on tumor purity and immune escape, we propose that different CD163 expression groups respond differently to immunotherapy in CRC." (PMID 36551651, 2022). "Although multiple experimental mAbs have shown evidence of target specificity, characterised by increased serum CSF-1 and reductions in M2-associated CD163+, CD206+, and CSF-1R+ TAMs, insufficient anti-tumour activity has been displayed." (PMID 35020853, 2022). "In response to Nanog+F10-EVs, immunoreaction was observed in liver, indicating the specific decrease in the number of tumor-promotive CD163-positive macrophages." (PMID 35200587, 2022). "We also observed phenotype shifting of TAMs from immune-suppressive CD68+CD163+ TAM2 to pro-inflammatory/anti-tumor CD68+CD163-TAM1." (PMID 36686751, 2022). "A recent study on patients-derived GB sections revealed the high infiltration of CD163+ cells (M2-like TAMs) in both the tumor core (TC) and peritumoral area (PTA)." (PMID 35682991, 2022). "Compared with the Ctrl group, the number of tumor-infiltrating CD163+ (P = 0.03) and CD206+ (P = 0.03) macrophages was significantly higher in the dCKO group." (PMID 35853880, 2022). "Compared with the Chemo group, the Io+Chemo group demonstrated a significantly higher M1 macrophage density (CD68+CD163- cell subset) ratio in the tumor to that in the stroma (P = 0.0446)." (PMID 36275670, 2022). "One study found that tumour density of TAMs expressing M2 marker CD163 negatively correlated with patient overall survival (OS)." (PMID 35020853, 2022). "In this study, CD163+ M2 macrophages were mostly infiltrated in the tumor stroma, and the cells were greater in number in the LPLs) and LSCC) than in the VP)." (PMID 35280439, 2022). "Macrophages in the tumor microenvironment predominantly exhibit an M2 phenotype with high CD163 expression." (PMID 36010928, 2022).
tumor (continued). "Increased infiltration of both CD68+ and CD163+ TAMs in tumor mass correlated with decreased survival of 174 patients with gastroesophageal adenocarcinoma from Sweden." (PMID 36686729, 2022). "First, virtually all reported studies used trained pathologists to analyze tumor specimens, while we developed methodology which allowed for the operator-independent identification of cancer cells and CD163+ TAMs in the tumor stroma." (PMID 35053472, 2022). "CD163/CD68 ratio was the highest at the MF tumor stage and Sézary syndrome, indicating M2 polarization with disease progression." (PMID 35055124, 2022). "While the percentage of tumor-associated CD68+ macrophages is comparable across indications, diffuse midline gliomas have the lowest number of infiltrating CD8+ T cells and CD163+ macrophages, which contributes to its immunosuppressive phenotype." (PMID 35464481, 2022). "He at al. also identified that the intensity of the infiltration of CD68+ and CD163+ macrophages was positively correlated with lymph-node involvement and tumor size." (PMID 36230558, 2022). "These two markers were related to different tumor clinicopathological parameters: CD163+ TAMs correlated with higher tumor grade and with basal-like phenotype, while CD206+ TAMs were associated with smaller tumor size, but not with TNBC molecular subtypes." (PMID 36230752, 2022). "Our data report a strong correlation between GPX7 expression with the M2 macrophages markers (CD163, VSIG4, MS4A4A), implying a potential role for GPX7 in the polarization of tumor-associated macrophages (TAM) in LGG169." (PMID 35440701, 2022). "A reclustering analysis of macrophages distinguished macrophages into two cell types, M1 (HLA-DQA2+) and M2 (CD163+), among which the tumor-infiltrating macrophages were primarily of the M2 type." (PMID 35894206, 2022). "Particularly, the M2 phenotype (CD163) with anti-inflammatory activity contributes to a favorable microenvironment for tumor development while the M1 (CD68) proinflammatory phenotype contributes to a restrictive one." (PMID 36451810, 2022). "For example, in a syngeneic ovarian cancer mouse model, whilst CD163+ Tim4+ TRMs were found to be indispensable for tumour progression, Ccr2−/− mice exhibited unperturbed disease." (PMID 35020853, 2022). "Among them, Module2 (highly express RNASE1, C1QA, CD163, CD14, C1QC, FCGRT, and MS4A7) and Module10 (highly express APOC1, CTSB, CTSL, and TYROBP) are more likely to display the characteristics of tumor-associated macrophages (TAMs)." (PMID 35990663, 2022). "The present work investigated the influence of the different factors VEGF, Ki-67, COX2, M-CSF, GM-CSF, CD68, and CD163 on tumor volume and growth as well as on clinical parameters, such as age and hearing, in a cohort of 173 patients using mRNA data and IHC." (PMID 36139588, 2022). "Remarkably, we observed that FOXP3+ Treg cells and TREM2+CD163+ macrophages colocalized within the tumor ecosystem by employing multicolor immunofluorescence staining." (PMID 35359989, 2022). "In lung metastases, T cells interacted with CD163+ macrophages as dyads and clusters at the brain-tumor interface and within the tumor itself and as clusters within the necrotic core." (PMID 35316217, 2022). "CD163+ cells were distributed in the tumor parenchyma (68/144, 47.2%), tumor stroma (58/144, 40.3%), and perivascular area (18/144, 12.5%)." (PMID 36361871, 2022). "We observed that TBC1D8 knockdown significantly down -regulated the surface markers of M2 tumor-associated macrophages (TAMs) (CD206 and CD163) in THP-1 macrophages." (PMID 35918393, 2022). "The main cell clusters included T cells (CD3E and CD3D), B cells (CD19), natural killer cells (NCAM1, FCGR3A and KLRD1), myeloid cells (CD86 and CD163) and tumor cells (EPCAM, KRT8 and KRT18)." (PMID 36497182, 2022).
tumor (continued). "Multiplex immunohistochemistry assay was performed in seven patients (P01-P06 and P09) to simultaneously measure the expression of the multiple surface markers associated with the tumor microenvironment, such as PD-1, PD-L1, CD3, CD8, CD68, CD56 and CD163." (PMID 35172862, 2022). "Its levels are elevated in tongue leukoplakia tissues with high CD163+ M2 macrophage infiltration in the tumor microenvironment that provides an immunosuppressive microenvironment for tumor growth." (PMID 36555876, 2022). "Regarding the tumor malignancy grade, the increased percentage of total CD163+ macrophages, especially those located in stroma, were positively associated with poorly differentiated FMC, supporting its negative prognostic role." (PMID 36010653, 2022). "Specifically, within the SDHB tumours there was a higher proportion of CD163 expressing macrophages (M2, P = 0.02) in aggressive SDHB tumours, correlating with a higher Ki67 index." (PMID 35975974, 2022). "Immunohistochemical staining for the M2 marker CD163 revealed a high influx of CD163 positive cells to the base of gp130F/F tumours, compared to a lower cell density in the antra of gp130F/FIL33−/− mice (lower left vs. right panel)." (PMID 35677533, 2022). "The present study builds on past progress of cell density-based tumor analyses and provides new insights into the prognostic significance of spatial proximity of CD163+ TAMs to cancer cells using objective and quantitative methodologies." (PMID 35053472, 2022). "After treatment with ADT, CD68+ and CD163+ macrophage infiltration was increased in the tumor tissues of patients." (PMID 36439479, 2022). "The decrease in CD163 mRNA was confirmed by IHC in all samples and a set of paired samples where a baseline biopsy from the lung had ~7% of the tumor area positive for CD163 compared to ~1% in a biopsy from the same lesion at progression (Day 125)." (PMID 36075914, 2022). "CD8+, GZMB+, CD68+ and CD163+ cells showed significant correlation throughout the majority of assessed tumour regions (centre, front and microenvironment)." (PMID 36114487, 2022). "While M1 macrophages (iNOS-positive) associate with anti-tumor activity, leading to the activation of adaptive immune cells, M2 macrophages (CD163) inhibit immune function, supporting tumor proliferation and metastasis." (PMID 36010653, 2022). "CD163+ M2 macrophages are a driving factor in tumor growth, angiogenesis and metastasis and the repolarization towards M1 macrophages presents a novel approach in oncologic treatment." (PMID 36605202, 2022). "Compared with the primary tumor, liver metastases express more immune cells in the peritumor area more than or equal to 150 μm away from the tumor, especially CD163-labeled macrophages, which have the highest expression in the PT region." (PMID 36195882, 2022). "Overall, we conclude that M2 macrophage infiltration is enhanced in PDLIM2- positive tumour stroma, with CD163+ and CD206+ macrophages more strongly represented in these tumours than in PDLIM2-negative stroma." (PMID 36531051, 2022). "Since TAM infiltration increases pro-tumor functions such as angiogenesis and tumor burden, we wanted to look at the recruitment of M2-phenotype TAMs into the tumor microenvironment using CD163 (a common M2 marker)." (PMID 35461243, 2022). "Consistent with this, TAM treatment markedly increased the number of Toll-like receptors 4 (TLR4+) macrophages and decreased that of CD163+ macrophages in the tumor tissues." (PMID 35269804, 2022). "CD163+ M2 macrophages have been suggested to counteract tumor immunity by increasing immunosuppressive mechanisms including PD-L1 and IL-10 expression." (PMID 35204426, 2022). "Increased levels of tumor associated M2 macrophages (M2 TAM) in the pre-operative biopsy tissues, such as CD68 or CD163 positive macrophages, have been associated with reduced responses to therapy and more frequent non-pCR results." (PMID 36428702, 2022).